LGALS3 (galectin 3)
Diseases named in the same sentence as LGALS3 in open-access papers (continued):
Sharing a sentence is not in itself a finding about the gene and the disease.
tumor (continued). "In addition, H1299 cells were treated with recombinant galectin-3 (5 ng/ml) in tumor sphere medium and cultured for 12 days to investigate whether extracellular galectin-3 could augment sphere formation." (PMID 25669973, 2015). "Alternatively, a benefit in survival we found in stage 3 cancer patients with a higher avidity of TF-specific Abs might be the result of a more efficient blockade of TF antigen on circulating tumor cells, thus protecting against metastases through the inhibition of the TF/galectin-3 pathway." (PMID 26663951, 2015). "Moreover, except for H460, most NSCLC-derived tumor spheres had increased galectin-3." (PMID 25669973, 2015). "Given that the expression of TF antigen on tumor cells promotes metastasis by interaction with galectin-3 on the endothelial cells, it is logical to assume that the circulating TF-specific antibody may modulate this interaction via binding with TF antigen-positive circulating tumor cells." (PMID 26663951, 2015). "Thus, targeting galectin-3 expression in selected tumors may prove to be an effective strategy to control tumor growth." (PMID 24764473, 2013). "Besides secretion, galectin-3 could be released into the extracellular space following cell lysis, which does occur in tumor microenvironments, for example." (PMID 22216245, 2011). "Once localized to the cell surface, galectin-3 is capable of oligomerization, and the resultant cross-linking of surface glycoproteins into multimolecular complexes on the endothelial cell surface is reported to mediate the adhesion of tumor cells to the vascular endothelium." (PMID 20831833, 2010). "Also, some authors believe that galectin-3 immunoexpression in PTC may promote the release of tumor cells resulting in metastasis." (PMID 20181018, 2010). "In vivo, LGALS3 knockdown markedly increased tumor volume, whereas FBXL5 overexpression reduced tumor growth." (PMID 42093989, 2026). "The downregulation of cell adhesion proteins (ITGB1, LGALS3, LGALS3BP, SDCBP, PODXL, CDCP1) further suggests a potential impact on tumor cell attachment, migration, and invasion, contributing to the anti-metastatic effects of TSA." (PMID 40429900, 2025). "Key upregulated proteins included LGALS3 (Galectin 3), an established marker of thyroid malignancy 22, and POSTN (Periostin), which promotes tumor metastasis and angiogenesis." (PMID 40861812, 2025). "Using three spatially-enriched marker genes for each tumor subregion (CT: BCAN, CSPG5, TOP2A; Pseudo: HILPDA, IGFBP5, LGALS3; and MVP: MGP, LUM, THBS1) we identified distinct sub-populations of malignant cells from the scRNA-seq data." (PMID 41366031, 2025). "Binding of galectin-3 to checkpoint LAG3 and CTLA4 on immune cell surface prevents immune cell activation and penetration thus to aid tumour cell evasion from immune surveillance." (PMID 41023585, 2025). "Our findings align with previous work demonstrating that LGALS1, LGALS3, and LGALS9 bind to glycosylated ligands on T cells, inducing apoptotic cell death and attenuating anti-tumour immune responses." (PMID 41516291, 2025). "Their findings suggest that tumor cells increase the release of EVs expressing LGALS3BP, making galectin-3 a promising biomarker for diagnosis and disease monitoring." (PMID 40427551, 2025). "Next, active TAFs are fed back to tumor cells through the secretion of CCL2 and its receptor CCR2 on the membrane of LGALS3+ cells." (PMID 40600063, 2025). "The dual blockade of galectin-3 (Gal-3) and CD47 synergistically suppressed tumor growth, increased phagocytosis, repolarized macrophages, and increased T-cell immune responses." (PMID 40732268, 2025). "Our data demonstrated the presence of soluble Galectin-3 in the primary and ascitic HGSC tumor microenvironment, together with the presence of degranulated neutrophils." (PMID 39759523, 2024). "Galectin-3, basigin, S100A9, and fibronectin involved in TME–CRC–ECM crosstalk were found to be differently variated in both tumor regions." (PMID 39195201, 2024).
tumor (continued). "Significant correlations between ITGB1 and LGALS3 mRNA levels, and between ITGB1 and IL-10 mRNA levels, are observed in the LIHC normal and tumor tissues, and in normal liver tissues." (PMID 38793619, 2024). "Herein, we found that TREM2-mediated phagocytosis of tumor cells was dependent on the DAP12-Src-Syk signaling pathway, which was inhibited by galectin-3 in LLC CM." (PMID 39135069, 2024). "According to the available Clinical Proteomic Tumor Analysis Consortium (CPTAC) dataset, we determined the expression levels of LGALS3 protein in nine of the 23 cancer types." (PMID 38643145, 2024). "The LGALS3/JUN/ITGB1/SPP1 genes were highly expressed in MES-like GBM cells, and the expression of these genes was significantly upregulated with tumour progression." (PMID 39629136, 2024). "This study suggests that galectin-3 mediates the crosstalk between WNT/β-catenin and STAT3 signalling in tumour progression." (PMID 38990375, 2024). "The concurrent administration of galectin-3 and CD47 extensively promoted the remodeling of TAMs and phagocytosis, resulting in an increased T cell response and suppressed tumor growth in an in vivo experimental peritoneal metastasis model." (PMID 39519285, 2024). "Accordingly, we demonstrated herein that NExT are naturally functionalized with diverse receptors (PD1, LAG3, TIM3) that can interact with their corresponding ligands (e.g., PDL1, Galectin-3, FGL-1, MHCII, Galectin-9, HMGB1, Ceacam-1) within the tumor." (PMID 38730475, 2024). "A recent study demonstrated that a synergic expression of galectin-3 with CD47 in peritoneal metastatic cells is correlated with diffuse-type GC and tumor relapse." (PMID 39519285, 2024). "The clinical relevance of our experimental findings was supported by immunohistochemical staining analyses demonstrating that the expression of HDAC7, ITGB1, LGALS3 and CD44 was highest in GBM tumours and was negatively correlated with SOX8 expression." (PMID 39629136, 2024). "Similarly, G-CSF derived from galectin-3 may also promote tumor growth by stimulating angiogenesis." (PMID 39300154, 2024). "Then, we evaluated the correlation between expression of LGALS3 in tumor and gene expression levels of FOXP3, CD4, and CD8 in tumor and stroma area samples that were microdissected from FFPE samples." (PMID 37567864, 2024). "Galectin-3 can promote macrophage differentiation to an M2-like phenotype and inhibit CD8+ T cell-mediated anti-tumor effects." (PMID 39135069, 2024). "Significant correlations between the LGALS3 and IL-10 mRNA levels were observed in the LIHC normal and tumor tissues, and also in the normal liver tissues." (PMID 38793619, 2024). "Other ligands, including fibrinogen-like protein 1 (FGL1), galectin-3 (Gal-3), and liver sinusoidal endothelial cell lectin (LSECtin), have been identified to bind with LAG-3, thereby suppressing CD8-mediated anti-tumor responses." (PMID 38785789, 2024). "Galectin-3 with KRAS can induce PI3K activation as well as constitutive activation of the RAF/MEK/ERK signaling cascade, thereby regulating tumor cell functions." (PMID 36873388, 2023). "In addition, GB1211 reverses the galectin-3-induced inhibition of immune checkpoint inhibitors (pembrolizumab and atezolizumab) binding to programmed cell death protein 1 and PD-L1, thereby reducing tumor resistance to these agents and restoring response to immune checkpoint therapy." (PMID 36914828, 2023). "Altogether, these results suggest that galectin-3 regulates cancer stemness, and induces cancer-cell intrinsic inflammation by upregulating CXCR2, thereby increasing tumor progression." (PMID 36873388, 2023). "LGALS3 and G6PD were highly expressed in the CHI, S2-S4, and tumor groups, and PINK1 was highly expressed in the normal, S0-S1 and paracancerous tissues." (PMID 37180150, 2023).
tumor (continued). "Immunohistochemical analysis revealed that the tumor cells were diffusely positive for thyroid transcription factor 1 (TTF-1) and galectin 3, with more intense galectin 3 immunoreactivity in the solid/trabecular and papillary portions." (PMID 36973752, 2023). "We successfully performed flow cytometry and bulk-RNA-seq of tumour biopsies which showed an increase in percentage of intratumoural cells expressing MHCII, Galectin-3, CD8 or IgG." (PMID 36817448, 2023). "The interplay of galectin 3 of tumor cells and platelet glycoprotein VI (GPVI) promotes tumor metastasis, and Hsp47 enhances the interplay between tumor cells and platelets and further promotes tumor metastasis." (PMID 35689440, 2023). "Other known ligands are also galectin-3, fibrinogen-like protein 1 (FGF-1) and L-selectin presence on tumour cells." (PMID 36980527, 2023). "Beside tumor cells, other cells in the immunosuppressive tumor microenvironment (TME) produce galectin-3." (PMID 38259448, 2023). "In stage II tumors, however, a dramatic decrease in the expression of the Galectin-3 in both PIN and tumor sections was detected, with only 10.5% of these samples expressing this protein." (PMID 36936148, 2023). "The broad influence of galectin-3 on promotion of cancer progression led us to hypothesise that galectin-3 overexpression and secretion by cancer cells may influence the cellular secretion of proteases and thus contribute to tumour cell invasion and metastasis." (PMID 37055381, 2023). "Then, we picked out 8 HAIRGs (VEGFA, CTNNB1, PPARG, HSP90AA1, HMOX1, LGALS3, SPP1, and RAC1) from the 17 HAIRG model through the LASSO Cox regression, upregulated genes accounted for 7/8 in tumor tissue, which was shown by a heat map." (PMID 35069936, 2022). "Meanwhile, other members of the galectin family play similar roles, for example, high expression of galectin-3 promotes the expression of GLUT1 through the PI3K signaling pathway, which in turn enhances glycolysis in tumor tissues." (PMID 36428567, 2022). "A series of adhesion factors excreted by bone marrow endothelia such as selectins and galectin-3 were not only the vital mediator for hematopoietic stem cell (HSC) homing, they also actively participated in tumour cells usurping the bone." (PMID 35685372, 2022). "As galectin-3 interacts with and regulates other proteins, which contribute to EMT during tumor cell migration and invasion." (PMID 36713574, 2022). "Mechanistically, GCS-100 detaches galectin-3 from CD4+ and CD8+ tumor-infiltrating lymphocytes, boosts cytotoxicity and restores IFN-gamma secretion." (PMID 36703969, 2022). "The interaction of galectin-3 with T cell-expressed α3β1 integrin inhibits T cell proliferation and promotes the formation of a PDAC immunosuppressive tumor microenvironment." (PMID 36428567, 2022). "Galectin-3 is also more highly expressed in NSCLC and augments tumorigenesis, invasion, metastasis, and tumor immunity." (PMID 35681762, 2022). "There were no major changes in matrisome-associated proteins, except for the observed increase in the secreted factor HCFC1 and the ECM-affiliated protein, LGALS3, on the MDA-MB-231-seeded tumor scaffold." (PMID 35755802, 2022). "We also showed that probes ICAM1, calreticulin, PD-L1, neuropilin-1, galectin-3 and MPO were spatially associated with immunogenic cell death and, together with the enriched standard cell types, they might serve as an early predictive biomarker of induced anti-tumor immunity in situ." (PMID 35788566, 2022). "Galectin 3 (LGALS3), which is regulated by miR-493, is also overexpressed in CTs and correlates to increased tumor aggressiveness." (PMID 33986726, 2021). "The protein expression of galectin-3, TIMP-1, and NAG-1 was higher in tumor tissues than in normal tissues." (PMID 34208730, 2021). "The same study demonstrated that both LGALS3 and LGALS3BP were significantly increased in more aggressive HCC tumours." (PMID 34794390, 2021).
tumor (continued). "Galectin-3 (Gal-3), liver sinusoidal endothelial cell lectin (LSECtin) and fibrinogen-like protein 1 (FGL1) are LAG-3 ligands that are frequently expressed in the tumor environment." (PMID 34575943, 2021). "PDAC-derived galectin-3 (Gal-3) induces production of IL8 through integrin/NF-κB signaling from stromal cells, which mediate remodeling of TME and promote tumor growth and metastasis." (PMID 33406733, 2021). "In the TCGA cohort, we observed similar correlations: M3 tumours showed a higher expression than D3 tumours for LAG3, LSECtin, Galectin-3, HLA-DRalpha, HLA-DQalpha, and HLA-DPalpha (all p = 0.001, Mann–Whitney U test)." (PMID 34503258, 2021). "In addition, the suitability of [68Ga]-3 for the determination of galectin-3 levels was investigated, but the use of this radiotracer resulted in moderate tumor uptake, which may be explained by the fact that this lactosamine derivative is not a sufficiently specific ligand for galactin-3 receptor." (PMID 34959383, 2021). "An interaction between the tumor cells and the ECM protein elastin is mediated by two elastin-binding proteins (S-gal and galectin-3) and two laminin receptors." (PMID 34827210, 2021). "As such, tumor heterogeneity, especially with regards to the diversity, density and steric complementarity of cell surface adhesion molecules (e.g., TF antigen, Cadherins, galectin-3, EpCAM, Na+/K+-ATPase, and glycoprotein 100, etc.)may prove to be extremely difficult to address in the clinic." (PMID 34070233, 2021). "The expression of OPG was higher in normal tissues, whereas that of galectin-3 and TIMP-1 was higher in tumor tissues." (PMID 34208730, 2021). "The capability of Gal-3 to bind activated antigen-committed CD8+ T cells is only possible in the tumor microenvironment through Gal-3 binding to LAG-3, and thus LAG-3 expression is necessary for galectin-3-mediated suppression of CD8+ T cells in vitro." (PMID 32408492, 2020). "Specifically, the localisation of glycosylated M2BP as M2BPGi, galectin-3 and M2BP mRNA was evaluated in HCC tissues resected from fibrotic liver, and the tumour-promoting effects of M2BPGi were analysed in vitro and in vivo." (PMID 32624579, 2020). "In summary, we show that Galectin-3 modulated angiogenesis- and EMT-driven metastasis via activation of the β-catenin signalling cascade by targeting IGFBP3 and vimentin in the HCC tumour microenvironment." (PMID 32801345, 2020). "They showed that galectin-3 propagates the VEGF pathway, leading to increased angiogenesis and expansion of the tumor." (PMID 32033052, 2020). "In all, Galectin-3 and Galectin-1 support high fidelity and prolonged Ras signaling downstream to Raf or PI3-kinase, and they also control Ras-regulated tumor suppressor, e.g., Bcl2 or β-catenin, thereby supporting tumor survival." (PMID 31861875, 2019). "Galectin-3 is widely expressed in different cell types; thus interaction with LAG-3 serves to broaden LAG-3's immune regulatory impacts on tumor-infiltrating CD8+ T cells within the TME." (PMID 30603054, 2018). "Others claimed that extracellular galectin-3 induces apoptosis of CD4 or CD8 T cells in the tumors and can suppress IFN-γ secretion of human cytotoxic T cells in tumor." (PMID 29849497, 2018). "Although CD4+CD25hiFoxP3+ T cell depletion strategies turned out not to be robust enough to allow implementation into a clinical protocol aiming at improved generation of tumor-reactive T cells, inhibition of IDO and galectin-3 proved to be successful." (PMID 28401257, 2017). "Galectin-3 is a mammalian lectin that is up-regulated in HCC and involves in tumour progression and poor prognosis in HCC." (PMID 28701735, 2017). "To further examine the role of the extracellular matrix in IFNγ trapping by galectin-3, we partially degraded the ECM by injecting in the center of the tumor a low dose of collagenase D together with IFNγ." (PMID 28986561, 2017).
tumor (continued). "Then we assessed Galectin-3 protein levels in 57 paraffin-embedded matched CRC and adjacent non-tumor colon tissues with follow-up data for patients." (PMID 28146425, 2017). "We found that the tumor cell produced IDO and/or galectin-3, and the accumulation of CD4+CD25hiFoxP3+ T cells suppressed the expansion of tumor-specific T cells in the MLTC." (PMID 28401257, 2017). "Compared to tumor sections prepared by control A2780 cells, the expression of NICD1, NANOG, OCT4 and SOX2 was significantly increased in those prepared by galectin-3 overexpressing A2780 cells." (PMID 27626163, 2016). "Moreover, while most studies have examined one galectin at a time, focusing largely on galectin-1 and galectin-3, it is now well established that normal and tumor cells express more than one galectins, and that multiple galectins could be released in the tumor microenvironment (TME)." (PMID 26933916, 2016). "Our results together with accumulating evidence about the interaction between tumor-cell glycoprotein such as mucin MUC16 and lectin, galectin-3 for instance in PDAC will pave new ways to interfere with cancer progression." (PMID 27382435, 2016). "Galectin-3, a one-CRD galectin belonging to the chimera type, shows pleiotropic biological functions in cell growth, apoptosis induction, tumor progression, and pre-mRNA splicing." (PMID 25669973, 2015). "Galectin-3 and GLUT-1 (hypoxia marker) expressions were assessed by immunohistochemistry in the tumor xenografts." (PMID 26222311, 2015). "Silencing of genes with reported immune-regulatory function, namely PD-L1, CEACAM-6, and galectin-3 (GAL-3), strongly reduced luciferase activity only in the cytotoxicity setup, whereby PD-L1 showed a higher impact on tumor lysis." (PMID 25691366, 2015). "Altogether, these results suggest that the shift towards a cytoplasmic and membranous localization of galectin-3 favors resistance to apoptosis and malignancy of CMT-U27 tumor cells under hypoxia." (PMID 26222311, 2015). "Knockdown of galectin-3 in lung adenocarcinomas decreased stemness-related genes like Oct4, Sox2, Nanog, and CD133, as well as the capability of tumor initiation in vitro and in vivo." (PMID 25669973, 2015). "In this analysis, we used galectin-3, HBME-1, CK19, Ki67 and cyclin D1 to evaluate the borderline nature of this tumour." (PMID 25907675, 2015). "In C2GnT1-expressing bladder tumor cells core 2 O-glycans present on MHC class I-related chain A are bound to Galectin-3 that reduced the affinity for the activating NK cell receptors NKG2D, thereby impairing NK cell function and anti-tumor activity." (PMID 24592356, 2014). "Here we studied four immunohistochemical tumor markers (HBME-1, MIB-1, CK19, and Galectin-3) in thyroid of mice housed in the Mouse Drawer System and maintained for 90 days in the International Space Station." (PMID 25328888, 2014). "Correlation analysis of galectin-3 expression and micro-vessel density (MVD) showed that galectin-3 expression in tumor cells stimulates angiogenesis." (PMID 25260879, 2014). "Galectin-3 is in accordance overexpressed in necrosis-surrounding cells both in primary and in metastatic CMT lesions despite downregulated in other tumor areas." (PMID 24563633, 2014). "The tumor also expresscs Vimentin, PGP9.5, NKI/C3, and CD68 while some markers such as Inhibin-α, Calretinin, Galectin-3, and HBME show varying rates of staining." (PMID 22132340, 2011). "Parameters of the tumour microenvironment, such as the frequency of cells expressing cyclo-oxygenase-2 (COX-2), caspase-3 and galectin-3, and microvascular density, were determined by immunohistochemistry." (PMID 20465821, 2010). "Inhibiting LGALS3 could potentially synergize with chemotherapy to break through stromal barriers, while blocking CD55 could restore complement-mediated tumor lysis." (PMID 40723289, 2025).